BUB1 (BUB1 mitotic checkpoint serine/threonine kinase)
Diseases named in the same sentence as BUB1 in open-access papers (continued):
Sharing a sentence is not in itself a finding about the gene and the disease.
ZIKV infection (1 paper, 2018). "Genes associated with cell differentiation and proliferation, such as BUB1, DLGAP5, PBK and CEP55 (Cluster 3) were upregulated during DENV infection but not ZIKV, while EGR1, HBEGF and MAFB (Cluster 4), were up-regulated at d17 POS during ZIKV infection." (PMID 30596671, 2018).
cancer (164 papers, 2007 to 2026). A tumor composed of atypical neoplastic, often pleomorphic cells that invade other tissues. "For instance, CDK1 and BUB1 have been associated with aggressive behavior in cancers, but their direct involvement in environmental chemical–induced lung carcinogenesis had not been demonstrated." (PMID 41181148, 2025). "Existing evidence has established a positive correlation between BUB1 with PD-L1 40, and our pan-cancer analysis confirms SGO1 is linked to PD-L1 across most cancers." (PMID 40861810, 2025). "BUB1 activity has been associated with cancer progression through cell proliferation, migration, and epithelial–mesenchymal transition (EMT) activation." (PMID 40723917, 2025). "Disruptions or mutations in BUB1 can lead to chromosomal instability and contribute to the development of various cancers." (PMID 41378098, 2025). "In transgenic models, BUB1 overexpression promotes chromosomal missegregation and aneuploidy, leading to an increased predisposition to spontaneous cancer." (PMID 40180891, 2025). "We performed a pan-cancer analysis of the mitotic checkpoint budding uninhibited by benzimidazole 1 gene BUB1, in the attempt to ascertain its diagnostic and prognostic values, specifically in the context of drug response." (PMID 38396175, 2024). "On the basis of BUB1’s association with aggressive cancer subtypes, we explored the association between BUB1 expression and clinico-pathological features by Chi-square analysis." (PMID 38396175, 2024). "Overall, these results indicate that BUB1 expression is associated with clinical outcomes according to the drug administered, with cancer-specific effects of drugs preferentially involved in DNA-related processes." (PMID 38396175, 2024). "BUB1 has been reported to be closely associated with the occurrence of various cancer types, including gastric cancer, breast cancer, and PDAC." (PMID 38672622, 2024). "Proliferative scores showed a modest association with BUB1 expression (12 cancers out of 25, median = 0.22, range 0.08–0.44)." (PMID 38396175, 2024). "Our analyses showed that high BUB1 expression was associated with OS in eight cancers including ACC, KIRC and KIRP and DFS in 10 cancers including ACC and KIRC." (PMID 39048649, 2024). "Given the differential expression of BUB1 in distinct cancer subtypes associated with aggressiveness, we sought to determine the prognostic relevance of BUB1 expression." (PMID 38396175, 2024). "The highest AUC values closest to 1.0 (i.e. with the highest sensitivity and specificity) were achieved by UCS, CESC, GBM, BRCA, READ, and OV, with most cancers averaging above 0.8, indicating a potential diagnostic use of BUB1." (PMID 38396175, 2024). "In conclusion, we found diagnostic and prognostic applications for BUB1 expression in cancer, and predicted drugs that are associated with differential responses based on BUB1 levels." (PMID 38396175, 2024). "Approximately 2% of cancer patients have BUB1 gene mutations, including deletions, amplifications and deep deletions." (PMID 39048649, 2024). "As a mitotic checkpoint serine/threonine kinase, BUB1 overexpression has been associated with increased cellular proliferation and has been implicated in several cancers." (PMID 36551837, 2022). "Long-term follow-up and characterization of more patients are necessary to clarify a potentially enhanced cancer risk and to fully describe the phenotypic spectrum associated with BUB1-related neurodevelopmental disorders." (PMID 35044816, 2022). "BUB1 plays a role in oncogenesis, as indicated by the occurrence of BUB1 mutations, as well as differential BUB1 gene and protein expression in cancer tissues and cell lines." (PMID 34884561, 2021). "Budding uninhibited by benzimidazoles 1 (BUB1) encodes serine/threonine protein kinases that are crucial in spindle assemble checkpoint, as well as investigations have demonstrated the role in oncogenesis of BUB1 mutation in several cancers." (PMID 34257549, 2021).
cancer (continued). "BUB1 mutations are only occasionally found in cancer, but BUB1 overexpression is a frequent phenomenon that is associated with high proliferative activity of tumor cells and a poor clinical outcome in various solid cancers." (PMID 32781708, 2020). "As a common candidate key gene, BUB1 had a mitotic serine/threonine kinase checkpoint that was up-regulated in numerous cancers and associated with tumorigenesis, proliferation, and metastasis." (PMID 33160391, 2020). "As for other mitotic checkpoint proteins, BUB1 abnormality is associated with various types of cancers." (PMID 32781708, 2020). "Inhibition of BuGZ results in loss of both Bub3 and its binding partner Bub1 from kinetochores, and lethal chromosome congression defects in cancer cells." (PMID 28553202, 2017). "BUB1 possibly functions in the DNA damage response, and mutations in this gene have been associated with aneuploidy and several forms of cancer." (PMID 26468983, 2015). "Altered expression of BUB1 is associated with therapy failure and death in patients with multiple types of cancer." (PMID 24758163, 2014). "An extensive search for mitotic-checkpoint defects in human cancers has uncovered very infrequent mutations of mitotic-checkpoint genes and more frequent altered expression of mitotic-checkpoints genes BUB1, BUBR1, BUB3, MAD1, MAD2 [reviewed in Ref." (PMID 24377086, 2013). "Mutation or aberrant BUB1 expression is associated with chromosomal instability, aneuploidy, and human cancer." (PMID 24025726, 2013). "Insufficiency of Bub1 increased cancer risk in mouse which showed higher frequency of aneuploid cells." (PMID 23805780, 2013). "Deregulated Bub1 expression and its kinase activity have been associated with chromosomal instability, aneuploidy, and several forms of human cancer." (PMID 22852086, 2012). "For BUB1, nearly half of the cancer-associated substitutions are mapped onto regions that are predicted to be of low structural complexity." (PMID 20888775, 2011). "Nearly 50% of the BUB1 substitutions associated with cancer can be mapped onto regions that are predicted to be mostly disordered, thereby opening the possibility that substitution of these residues impairs protein–protein interactions." (PMID 20888775, 2011). "Deletions, insertions and point and silent mutations associated with aneuploidy, chromosome instability and cancer occur throughout the BUB1 and BUBR1 sequences." (PMID 20888775, 2011). "A role for BUB1 in oncogenesis is indicated by the occurrence of BUB1 mutations, differential BUB1 gene and protein expression in cancer tissues and cell lines, and the formation of spontaneous cancers in mice that express hypomorphic alleles." (PMID 20888775, 2011). "We also describe the mapping of cancer-associated and chromosome-segregation-deficient BUB1 and BUBR1 mutations onto existing structures." (PMID 20888775, 2011). "Other genes associated to other cancers (e.g. BUB1 in bladder, MAD2L1 in breast) are involved in spindle checkpoint." (PMID 19753302, 2009). "Notably, overexpression of genes involved in the mitotic spindle checkpoint, such as NUF2, MAD2L1, and BUB1, has been linked to chemotherapeutic responses in various cancer types." (PMID 40643514, 2025). "Notably, we also identified a significant association of BUB1 with aggressive molecular subtypes and clinical features in different cancers, as well as phenotypic markers (i.e. hypoxia, stemness, and proliferation)." (PMID 38396175, 2024). "BUB1 mutation frequently occurs in cancer and leads to tumorigenesis." (PMID 39048649, 2024). "Here, we explored the potential of the mitotic checkpoint kinase BUB1 expression as a cancer biomarker and particularly its association with drug responses, stemming from previous studies on BUB1 dysregulation in cancer and its potential exploitation for therapeutic purposes." (PMID 38396175, 2024).
cancer (continued). "Furthermore, knockdown of DAB2IP in T47D cells resulted in an increased expression of BUB1, which has been associated with the maintenance of cancer cell stemness." (PMID 39418101, 2024). "Gene Ontology enrichment analyses revealed that BUB1 overexpression in cancer is associated with biological processes related to mitosis and chromosome segregation machinery, reflecting the mechanisms of action of drugs with a differential effect based on BUB1 expression." (PMID 38396175, 2024). "The role of BUB1 in excessive proliferation has not only been implicated in cancer but also in 3T3-L1 cells, where steroid receptor RNA activator (SRA) plays a modulatory role in assisting withdrawal from the cell cycle during the terminal stages of adipogenesis." (PMID 36551837, 2022). "High expression of the mitotic kinase BUB1 is associated with the occurrence and development of several cancers, although the relationship between BUB1 and bladder tumorigenesis remains unclear." (PMID 34852826, 2021). "BUB1B (BUB1 mitotic checkpoint serine/threonine kinase B) encodes a kinase involved in spindle checkpoint function and mitosis and plays an important role in the development of many types of cancer." (PMID 32528520, 2020). "Both proteins AURKB and BUB1 are linked in literature with the poor prognosis of different cancers." (PMID 32564237, 2020). "Cell cycle associated proteins are frequently aberrantly expressed in cancer and can be targeted using small molecular inhibitory compounds such as novel inhibitors of the BUB1-Polo-like-kinase 1 interaction and other cell cycle kinase inhibitors currently tested in preclinical studies." (PMID 29100315, 2017). "Bub1 (budding uninhibited by benomyl) is a serine/threonine kinase that has a function in the mitotic spindle checkpoint and is mutated in certain types of human cancer." (PMID 19450280, 2009). "In this particular case, we speculate that treatments with vinca alkaloids should be more efficient in those cancers where BUB1 is mutated." (PMID 20015360, 2009). "One possibility is that cancer-associated mutations of the N-terminal domain of BUB1 impair stabilizing interactions with BUB1 residues C-terminal to this domain that are not present in the crystallized protein (for instance, with those located in the adjacent BUB3 binding region)." (PMID 19141287, 2009). "Moreover, alternative strategies to subvert SAC, by knockdown of Bub1, BubR1, Mad2 or Aurora B caused cell death much more efficiently in tetraploid than in diploid cancer cells." (PMID 18159231, 2007). "High BUB1 expression has been associated with promotion of hypoxia-mediated stemness in lung cancer, which is tightly linked to tumour-sustaining angiogenesis, in line with our results showing hypoxia and stemness scores as highly correlated with BUB1 expression in the majority of cancers analysed." (PMID 38396175, 2024). "Budding uninhibited by benzimidazole 1 (BUB1) is a conserved mitotic checkpoint serine/threonine kinase, which has been recognized as an oncogene in cancers." (PMID 40914946, 2026). "BUB1 is a mitotic checkpoint serine/threonine kinase, which has been identified to be an oncogene in various types of cancers." (PMID 40914946, 2026). "BUB1 mitotic checkpoint serine/threonine kinase B (BUB1B) has been found to participate in cancer progression." (PMID 41163302, 2025). "The pan-cancer patterns, immune correlations, and BUB1 interaction uncovered here provide a roadmap for targeting SGO1 in precision oncology, either as a standalone biomarker or in combination with immune/DNA-damaging therapies." (PMID 40861810, 2025). "Recently, it was demonstrated that the inhibition of BUB1 activity sensitized cancer cells to the effect of docetaxel and paclitaxel in vitro and in vivo models." (PMID 40723917, 2025). "Long-term crystal violet assays further indicated a notable reduction in the 2D clonogenic capacity of BUB1-deleted cancer cells." (PMID 40180891, 2025).
cancer (continued). "This systematic approach unveils a cohort of verifiable genes, among which BUB1, a mitotic checkpoint serine/threonine kinase, emerges as a high-confidence hit in cancer cells." (PMID 40180891, 2025). "BUB1 was negatively correlated and BUB1B was positively correlated with cancer-associated fibroblasts and endothelial cell infiltration." (PMID 39048649, 2024). "Given the cancer‐promoting effect of these genes, how BUB1 affects the changes of these chromosomes need further study." (PMID 38498903, 2024). "BUB1 was associated with overall survival (OS) in eight cancers and disease-free survival in ten; BUB1B was associated with OS in nine cancers and DFS in eleven." (PMID 39048649, 2024). "Kaplan–Meier analyses subset by drug revealed significant associations with OS in several cancer sites, which were further validated by multivariate analysis (MVA) to assess BUB1 expression as an independent variable." (PMID 38396175, 2024). "Similar pro-apoptotic responses have been reported by our group and others in response to BUB1 inhibition that emphasize a potential commonality in the molecular responses triggered by BUB1 across different cancers." (PMID 39409911, 2024). "BUB1 was found to be overexpressed in the majority of cancers, and particularly elevated in clinically aggressive molecular subtypes." (PMID 38396175, 2024). "BUB1 inhibition reduced tumor xenograft growth and sensitized cancer cells to taxanes, ATR, or PARP inhibitors, confirming BUB1 as a therapeutic target for enhancing the efficacy of chemotherapies and targeted therapies." (PMID 39409911, 2024). "BUB1 is a mitotic checkpoint serine/threonine kinase that promotes cell proliferation in various cancers." (PMID 39045407, 2024). "BUB1 mitotic checkpoint serine/threonine kinase B (BUB1b) has been unequivocally identified as an oncogene in various cancers." (PMID 39043653, 2024). "Several drug associations in the clinical analysis of the TCGA cohort showed cancer-specific patterns of sensitivity/resistance, which may be attributable to the heterogeneity of patient data, as well as differences in clinical and phenotypic features associated with BUB1." (PMID 38396175, 2024). "Hypoxia scores were significantly correlated with BUB1 expression in 19 cancers out of 25, with a median Pearson correlation of 0.41 (range 0.12–0.82); stemness scores were correlated in 24 cancers with a median of 0.47 (range 0.1–0.83)." (PMID 38396175, 2024). "BUB1 was found to be overexpressed in the majority of cancers of the TCGA dataset, also highlighting a potential use as a diagnostic tool." (PMID 38396175, 2024). "In terms of prognostic value, the expression of BUB1 bore differential clinical outcomes depending on the treatment administered in TCGA cancer cohorts, suggesting sensitivity or resistance, depending on the expression levels." (PMID 38396175, 2024). "Pan-cancer analysis revealed that high expression of BUB1 and BUB1B was associated with poor prognosis and associated with immune infiltration in various cancers." (PMID 39048649, 2024). "We interrogated the expression of the BUB1 gene in 25 cancers of the TCGA cohort compared to unmatched healthy tissues from the GTEx database and observed a widespread dysregulation of BUB1 in all cancers analysed." (PMID 38396175, 2024). "The proliferative signature of cancer cells is known to be causally linked to expression of a core set of pro‐proliferative genes including MYBL2, BUB1, and polo‐like kinase 1 (PLK1)." (PMID 38538106, 2024). "Our previous research has shown that BUB1’s kinase activity drives aggressive cancer phenotypes through TGF-β signaling." (PMID 39409911, 2024). "Although BUB1 expression has an impact on prognosis, cancer prognosis is influenced by multiple factors, including tumor stage, histological grade, genetic alterations, and molecular markers." (PMID 38672622, 2024).